CCL2 (C-C motif chemokine ligand 2)
Diseases named in the same sentence as CCL2 in open-access papers (continued):
Sharing a sentence is not in itself a finding about the gene and the disease.
glioma (continued). "Our investigation revealed a positive correlation between the expression of CLEC7A and monocyte chemoattractant factors (CCL2, CCL5) as well as factors implicated in M2 macrophage polarization (TGF-β1, CSF-1) in glioma samples obtained from both TCGA and CGGA databases." (PMID 38846954, 2024). "While CCL2 is a proven good marker that could define the progress and malignancy of gliomas accurately, its CSF level is an invasive procedure." (PMID 39030882, 2024). "Canine Treg migration was enhanced by CCL2 or by glioma cell line-derived supernatant." (PMID 38947002, 2024). "In addition to playing a role in direct TAM recruitment, CCL2 also induces microglial release of IL-6, which in turn increases glioma cell invasiveness." (PMID 38893093, 2024). "Another report showed that CCL2 induced MDSCs migration to support glioma development." (PMID 38216673, 2024). "Tumor-infiltrating lymphocytes (TILs) can often be dysfunctional and exhausted because of the factors released by the glioma and microenvironmental cells, which include TGF-β, IL-10, and CCL2, causing the recruitment of Tregs (regulatory T cells), MDSCs, and TAMs to the tumor site." (PMID 39409094, 2024). "Additionally, C1142, a rat/mouse chimeric monoclonal antibody, has been shown to neutralize CCL2 in a glioma mouse model, significantly reducing TAM numbers and improving survival." (PMID 38893093, 2024). "Importantly, canine Treg migration was significantly enhanced by canine glioma cell line-derived supernatant and later mitigated by an anti-CCL2 antibody." (PMID 39046599, 2024). "The chemokine ligand 2 (CCL2), also referred to as monocyte chemoattractant protein 1, is a potent inducer of chemotaxis and proliferation of microglia and other immune cells in the glioma microenvironment in human GBM." (PMID 37368789, 2023). "Effects of CCL2 on glioma cells thus warrant further clarification." (PMID 37153567, 2023). "Moreover, multiple fluorescence staining showed that BCL2A1, CD68 and CCL2 were coexpressed in glioma tissues." (PMID 37889551, 2023). "In addition, CCL2 is a known progression‐inducing factor in humans with gliomas and has been reported to be significantly upregulated in HGA." (PMID 37246729, 2023). "Similarly, CCL2-expressing glioma cells induced a 10-fold induction of Ox42-positive cell density in rat models, while tumors overexpressing CCL2 increased more than three-fold, leading to reduced survival in rats." (PMID 36230833, 2022). "One possible mechanism by which CCL2 recruits BMDM to the TME could be the binding of circulating CCL2 molecules to glycosaminoglycans in gliomas to establish a concentration gradient that guides monocytes toward the site of inflammation." (PMID 36275720, 2022). "A very recent study demonstrated that CCL2 promotes temozolomide (TMZ) resistance in glioma cells." (PMID 36077785, 2022). "Total TAM number may be associated with aggressiveness and poorer prognosis in GBM, and CCL2 expression promotes glioma growth in animals models in addition to being a negative prognostic factor in GBM." (PMID 35267626, 2022). "Also, a study revealed that IL-1β secreted by both microglia and macrophages stimulated the p38 mitogen-activated protein kinase (MAPK) pathway in glioma cells, which in turn results in augmented secretion of CCL2—the agonist for CCR2 on microglia." (PMID 35419058, 2022). "CCL2 is therefore playing a role in TME-driven enhancements to glioma “malignancy” and may impact individualized cancer responses." (PMID 35906273, 2022). "Using a preclinical glioma model, we demonstrate that CCR2+/CX3CR1+ cells are sourced from the bone marrow, suppress both CD4+ and CD8+ T cells, migrate to CCL2 and/or CCL7 in a CCR2-dependent manner, and are reduced in the glioma microenvironment through combination targeting of CCL2 and CCL7." (PMID 36685592, 2022). "CCL2 is overexpressed in various cancers, including glioma, prostate, and breast." (PMID 36712886, 2022).
glioma (continued). "As a result, TAM-derived CCL2 selectively attracts Tregs in the glioma microenvironment." (PMID 35267626, 2022). "Similarly, CCL2-expressing glioma cells produced a 10-fold increase in Ox42-positive cell density in rat models, while tumors overexpressing CCL2 increased more than three-fold, resulting in reduced rat survival." (PMID 35600367, 2022). "Likewise, this viral tegument protein augments C-C motif chemokine ligand (CCL) 2/monocyte chemoattractant protein 1 (MCP1) through transcriptional upregulation, which has been attributed to glioma tumor grade and recurrence." (PMID 35515137, 2022). "To evaluate whether KR158B tumor cells are active contributors in the recruitment of CCR2+/CX3CR1+ cells, we tested whether glioma cells produced and secreted CCL2 and CCL7." (PMID 36685592, 2022). "CCL2 and its receptor (CCR2) are involved in regulating the monocyte/macrophage migration from the blood circulation to the brain through the vascular endothelium and are key pathogenic factors in glioma progression." (PMID 36275720, 2022). "Upon validating CCR2+/CX3CR1+ cell migration to the conditioned media of KR158B and KR158B CCL2 KD glioma cell lines, we sought to determine whether the migration was exclusively mediated by CCL2 and/or CCL7." (PMID 36685592, 2022). "We identified an increase in CXCL1, CXCL8, and CCL2 upon combining glioma cells with glial cells." (PMID 35906273, 2022). "Furthermore, CCL2 is responsible for the recruitment of CCR4-expressing Tregs to the glioma microenvironment." (PMID 36275720, 2022). "Furthermore, a considerably extended OS was observed in mice with glioma, using a combination of anti-CCL2 antibody with temozolomide." (PMID 36146527, 2022). "In addition, overexpression of CCR2A (the receptor for CCL2) was detected in human GBM specimens compared with normal brain tissues and was associated with increased migration of glioma cells." (PMID 35884700, 2022). "There is a large number of macrophages infiltration in the glioma microenvironment, which is associated with a variety of factors secreted by tumor cells, including IL-4, IL-6, IL-10, TGF-β, microRNAs, macrophage colony-stimulating factor (M-CSF), and CCL2." (PMID 36483052, 2022). "While the responses are heterogeneous across seven patient-derived lines, interstitial flow significantly increases glioma cell proliferation and stemness while glial cells affect invasion and stemness, potentially related to CCL2 expression and differential activation." (PMID 35906273, 2022). "High abundance of CCL2 has been detected in glioma tumour tissue and cell-line supernatants by ELISA, and glioblastoma-patient peripheral blood Tregs could be recruited to glioblastoma-conditioned medium in a CCL2-dependent manner." (PMID 35464424, 2022). "CCL2 overexpression is observed in several types of cancer, including glioma and prostate cancer." (PMID 34638796, 2021). "In other words, these results clarified that MEX3A could promote the development of glioma, in which CCL2 may be involved." (PMID 33414423, 2021). "In a study of a mouse glioma model, M-MDSCs were found to be recruited to the tumor site by CCL2 that produced by microglia and macrophages in the TME, whereas MDSC infiltration into the tumor was significantly reduced in CCL2-deficient mice." (PMID 34527668, 2021). "Their results showed that in a mouse glioma model, tumors growing in CCL2-deficient mice did not maximize the accumulation of Treg and MDSC." (PMID 34630121, 2021). "Glioma-bearing mice treated with duloxetine (a serotonin-norepinephrine reuptake inhibitor) exhibited a significant reduction in the level of chemokine CCL2/MCP-1 and prevented TAM infiltration into the tumor mass." (PMID 34439380, 2021). "Notably, a strong correlation between infiltrating microglial cells and an increased expression of MCP-1 or CCL2 in the rat glioma model was observed." (PMID 34439380, 2021).
glioma (continued). "Our results demonstrated that MEX3A may promote the development of glioma through regulating CCL2 expression." (PMID 33414423, 2021). "The migration and accumulation of MDSCs into glioma TME has been reported to be mediated by CCL2." (PMID 33919732, 2021). "Besides, the biological functions of CCL2 in glioma have also been comprehensively investigated and have been understood to some extent." (PMID 33414423, 2021). "It has been reported that microglia cells and macrophages in the glioma microenvironment could secrete chemokine CCL2 to recruit CCR4+ Treg and CCR2+ ly‐6C+ Monocytic MDSCs and suppress tumor immunity." (PMID 34482648, 2021). "Moreover, OAT-1746 treatment affects the expression of genes involved in leukocyte chemotaxis (Ccl2, Ccl7, Ccl17) and supporting glioma migration and invasion (Cme1, S100a4 and Mmp14)." (PMID 34504786, 2021). "It recruits Treg cells towards glioma using attractants such as CCL2 and IDO." (PMID 34671362, 2021). "More importantly, we further illustrated that knockdown of CCL2 could alleviate or reverse the promotion effects of MEX3A overexpression on glioma, indicating its potential role as the downstream of MEX3A." (PMID 33414423, 2021). "Moreover, the gain-of-function study of MEX3A and phenotype “rescue” experiments of the MEX3A/CCL2 axis were used for verifying the regulatory effects of MEX3A/CCL2 in glioma." (PMID 33414423, 2021). "Subsequently, following the construction of a molecular interaction network revealing the potential linkage between MEX3A and CCL2, we deduced that CCL2 may be a downstream target of MEX3A in the regulation of glioma." (PMID 33414423, 2021). "We found high expression levels of CCL2 in GSCs and GSCs-derived glioma model." (PMID 32943658, 2020). "We assume that if the entire CCR2/CCL2 signaling axis is inflicted by antibody treatment, tumor growth is inhibited, while specific knockout of tumor microenvironmental cells by using a Ccr2-/- transgenic mice leads to enhanced glioma progression." (PMID 32668709, 2020). "In syngeneic and intracranial xenograft mouse models with GL261 glioma, administration of an anti-CCL2 antibody could block recruitment and decrease the number of both MDSCs and TAMs in the TME, leading to prolonged survival of tumor-bearing mice." (PMID 33374253, 2020). "Here, we studied the importance of paracrine signaling in the glioma microenvironment by focusing on the celecoxib-mediated role of chemokines C–C motif ligand 2 (CCL2), C-X-C ligand 10 (CXCL10), and their receptors, CCR2 and CXCR3, in GSCs and a GSC-bearing malignant glioma model." (PMID 32943658, 2020). "Moreover, CCL2 blockade in combination with the current standard TMZ-based chemotherapy also prolonged the survival of mice with glioma." (PMID 33374253, 2020). "It was shown that production of CCL2 by glioma cells can be stimulated by ATP and S100B." (PMID 32456359, 2020). "What is interesting, blockade of CCL2 function with a neutralizing antibody led to a reduction of the infiltration of microglia/macrophages and resulted in prolonged survival in a mice model of gliomas." (PMID 32456359, 2020). "Moreover, CCL2 expression in vitro was stimulated by pro-inflammatory cytokines IL-1β and TNFα in all glioma cell lines tested." (PMID 32456359, 2020). "CCL2 is a chemokine secreted by glioma cells to attract microglia and macrophages, which may further promote tumor growth and migration of malignant cells." (PMID 32456359, 2020). "Glioma-derived CCL2 acts on microglia with CCR2 and then produces IL-6 to stimulate the glioma." (PMID 33511267, 2020). "Thus, the presence of a large myeloid infiltrate in high-grade gliomas suggests an active passage of immune cells, driven by chemoattractant CCL2 and by a leaky barrier." (PMID 32642721, 2020). "However, this vicious process can be blocked or slowed down in glioma-bearing COX2-deficient and CCL2-deficient mice, through treatment with COX-2 inhibitors, and through MDSC-mediated immunosuppression." (PMID 32727419, 2020).
glioma (continued). "S100B may also encourage glioma growth by TAM chemoattraction and therefore, infiltration into gliomas through the upregulation of CCL2." (PMID 32722137, 2020). "For example, CCL2 was shown to be released from glioma cells." (PMID 32668709, 2020). "Since CCL2 is believed as the leading chemoattractant for macrophages, it may be suggested that CCL2 produced by glioma may mediate infiltration of these cells into the tumor microenvironment." (PMID 32456359, 2020). "TAMs could be recruited to tumor site by an interaction between CCL2 (constitutively produced by glioma cells) and its receptor CCR2 (expressed on TAMs), what confirms the importance of chemokines as the key players in GBM progression." (PMID 32456359, 2020). "In syngeneic and intracranial xenograft mouse models with GL261 glioma, administration of an anti-CCL2 antibody could block recruitment and decrease the number of both MDSCs and GAMMs in the TME, leading to prolonged survival of tumor-bearing mice." (PMID 31225500, 2019). "Overexpression of CCL2 was found in glioma cells and human tissues." (PMID 31207928, 2019). "In addition to antagonistic anti-CCL2 antibodies, minocycline has also been shown to inhibit the synthesis of CCL2 by TAMs and has the potential to block this immunosuppressive pathway to work synergistically with current glioma therapeutics." (PMID 31396227, 2019). "Using a murine GL261 glioma model, they showed that glioma cells are capable of secreting CCL2 to recruit MDSCs to the tumor site, and that tumor-derived CCL2 can further induce TAMs to secrete CCL2 leading to synergistic tumor immune suppression." (PMID 31396227, 2019). "Glioma cells can generate CCL2 to recruit monocytes/macrophages to the tumor site." (PMID 31183364, 2019). "CCL2, also known as monocyte chemotactic protein-1, is first identified in glioma cells as a cytokine that could induce the accumulation of TAMs around tumor tissues." (PMID 30619286, 2018). "Interestingly, the expression of CCL2 by some gliomas, which attracts CD8+ T-cells, has been exploited by investigators for adoptive T-cell strategies." (PMID 30740109, 2018). "In addition, several other chemokines are secreted by glioma cells, including monocytes chemoattractant protein-1 (MCP-1/CCL2) and stromal cell-derived factor-1(SDF-1/CXCL12)." (PMID 30413179, 2018). "CCL2 can trigger the release of IL-6 from microglia, promoting the glioma invasiveness." (PMID 29410971, 2017). "Finally, MCP-1 (CCL-2) showed the highest level of expression across our three glioma conditioned medias." (PMID 28666020, 2017). "The chemokine CCL2 can promote glioma tumor aggressiveness by promoting attraction of T regulatory cells (which suppress the lymphocyte anti-tumor effector function) and microglial cells (which can reduce the anti-tumor functions and secrete pro-invasive metalloproteinases)." (PMID 27716259, 2016). "Since our data showed that IL1β regulates CCL2 mRNA expression in glioma cells, we examined whether there was a correlation between IL1β and CCL2 mRNA expression levels in human GBM subtypes (from TCGA database) and murine GBM." (PMID 25987130, 2015). "CCL2 expression in glioma cells was nearly abolished by overexpression of PAX6." (PMID 26124920, 2015). "Anti-CCL2 therapy, for example, has shown success in prolonging survival in murine glioma models." (PMID 26217588, 2015). "CCL2 is a chemokine secreted by a variety of glioma cell lines and expressed in GBMs." (PMID 24202450, 2013). "Studies in rats suggests that low dose TMZ may also preferentially deplete Tregs, and lead to decreased CCL2 production by glioma cells and inhibition of Treg recruitment." (PMID 24202450, 2013). "Our present work suggests that, like macrophages, the CCL2 may also mediate lymphocyte infiltration in the glioma, and contribute to the level of aggressiveness." (PMID 22319587, 2012).
glioma (continued). "It is noteworthy that in murine glioma models, various vaccines strategies using CCL2, CpG, IL12-expressing stroma cells or IL23-expressing dendritic cells, induced an increased recruitment of NK cells at the tumor site, associated with better overall survival." (PMID 22980038, 2012). "The concept of selective affinity of TMZ towards monocytes was further confirmed in an animal experiment where either GL261 mouse glioma cells in a syngeneic model or U87 human glioma in a xenograft model were treated with systemic application of anti-CCL2 monoclonal antibody (MAb)." (PMID 23133490, 2012). "All biopsies of patients with glioma presented high expression of CCL2 in tumorigenic areas." (PMID 22319587, 2012). "As TMZ can reduce CCL2 secretion by glioma tumour cells, this could augment indirectly the efficacy of immunotherapy." (PMID 20953324, 2010). "Importantly, CCL2 expression in glioma correlates with poor prognosis." (PMID 38786066, 2024). "Here, the selective CCR2 antagonist RS504393 that inhibits the infiltration of immunosuppressive MDSC into the TME in a bladder cancer mouse model or CCL2 specific antibodies such as C1142 inhibiting tumor progression in a glioma model might be interesting novel agents." (PMID 37849753, 2023). "Therefore, we speculate that BCL2A1 may promote TAM infiltration in glioma by influencing chemokines, including CCL2, and affect the tumor microenvironment and tumor progression in glioma." (PMID 37889551, 2023). "Moreover, MEX3A has been suggested to promote tumor development in glioma by targeting CCL2." (PMID 35490173, 2022). "Interestingly, blockade of CCL2 function with a neutralizing antibody resulted in a reduction of the infiltration of microglia/macrophages and in prolonged survival in mice model of gliomas." (PMID 34200145, 2021). "In addition, the same glioma specimen section was used for CCL2, CD8 and PDL1 IHC staining." (PMID 35047393, 2021). "Moreover, CCL2 silencing by siRNA could repress the growth and angiogenesis in the U251 glioma cell line." (PMID 34638796, 2021). "The upregulated or downregulated MEX3A expression in glioma regulated the development and progression of glioma through targeting CCL2, which provided a reference that MEX3A may be served as a prognostic marker and a novel therapeutic target in glioma treatment." (PMID 33414423, 2021). "However, as the function of Rab27a in glioma is multifaceted, knocking down Rab27a may have unwarranted downstream effects aside from inhibition of EV release, such as changes in CCL2 expression, and should therefore be used with caution in glioma." (PMID 34298912, 2021). "Additionally, glioma-derived CCL2 recruits TAMs to the tumor, but at the same time takes part in a feed-forward mechanism, where it induces IL-6 production in microglia, which consecutively affects glioma cells by increasing their invasiveness." (PMID 34503065, 2021). "As high levels of CCL2 mRNA expression and the presence of CCL2 were observed in malignant glioma cells in studies in vitro, it became an interesting issue whether any changes of this chemokine also appear in CSF from glioma patients." (PMID 32456359, 2020). "Interestingly, while the CCL2/CCR2 signaling axis seems to be the main attractant for monocytes at the later stages of glioma growth, we show that Sdf1b/Cxcr4b signaling is responsible for macrophage infiltration during the initial stages of oncogene activation in the brain." (PMID 29465400, 2018).